CD4 (CD4 molecule)
Diseases named in the same sentence as CD4 in open-access papers (continued):
Sharing a sentence is not in itself a finding about the gene and the disease.
melanoma (continued). "Although we found antigen specific CD4+ T cells in the lungs of immune mice, the administration of a neutralizing anti-CD4 Ab during the memory phase did not abrogate protection against i.v. melanoma." (PMID 30319653, 2018). "Notably, both melanoma and NSCLC patients whose tumors exhibited increased inflammatory gene transcripts presented high CD4+ and CD8+ central memory T cell (CM) to effector T cell (Eff) ratios in blood." (PMID 30123214, 2018). "For instance, vaccination of melanoma patients with recombinant full-length NY-ESO-1 alone or in combination with the ISCOMATRIX adjuvant resulted in a strong induction of NY-ESO-1 specific antibodies, as well as an increase in specific CD4+ and CD8+ T cells." (PMID 29770138, 2018). "In addition, Tregs are deregulated in melanoma and inhibit the immune system through TGF-Δ, IL-10 and IDO over-production which dampens the activity of CD4+ and CD8+ lymphocytes, and NK cells." (PMID 29285320, 2017). "A fraction of the cell suspension was used to measure the different cell type proportions with flow cytometry (CD4 T, CD8 T, B, NK, melanoma and other cells comprising mostly stromal and endothelial cells), and the other fraction was used for bulk RNA sequencing." (PMID 29130882, 2017). "Clinical outcome of anti-PD-1/PD-L1 therapy was shown to correlate with MHC class II positivity in a unique subset of melanoma cells (typically MHC class II is expressed only on immune cells in solid tumors), as well as increased CD4+ and CD8+ TILs in melanoma patients." (PMID 29255458, 2017). "However, in our previous study using this same line of CD4+ T lymphocyte-specific SHP2 knockout (SHP2CD4−/−) mice, we found that SHP2 deletion promoted progression and metastasis of melanoma via IL-6-myeloid derived suppressor cells cascade." (PMID 27935860, 2017). "A population of expanded CD4+CD25highFoxp3+ Tregs expressing LAG-3 has been identified in the peripheral blood, in T cells of tumor-invaded lymph nodes and in T cells infiltrating the visceral metastasis of melanoma and sarcoma patients." (PMID 28404974, 2017). "In addition to this IDO-mediated regulation of anti-melanoma immunity, regulatory pDC have also been shown to drive TH2 and Treg differentiation of CD4+ T cells through cell–cell interactions via OX40L and ICOSL, respectively." (PMID 29209327, 2017). "Together, these data suggest that CD4+ and/or CD8+ T cells may contribute to controlling melanoma outgrowth by radio-immunotherapy." (PMID 27160390, 2016). "In addition, tumor-specific CD4+ T cells contribute to CD8+ T cell responses and their targeting enhances efficacy of DC vaccination for treatment of melanoma patients." (PMID 27853652, 2016). "Furthermore, Atg5 knockdown in human melanoma cells enhanced IL-6 production and proliferation of anti-tumorigenic CD8+IFN-γ+ and CD4+IFN-γ+ T cells." (PMID 27124579, 2016). "In both the B16 melanoma and MB49 bladder carcinoma murine tumor models, IL-17 produced by CD4+ T cells activated STAT3 in both tumor and stromal cells, leading to the expression of both anti-apoptotic and pro-angiogenic proteins within the tumor microenvironment." (PMID 27589814, 2016). "Although we did not assess different CD4 subsets (Th1, Th2, Th17, Treg), we nonetheless observed superior clinical outcomes with anti-PD-1/PD-L1 therapy in patients harbouring melanomas with MHC-II expression." (PMID 26822383, 2016). "No significant change in CD4+ T cells was observed in the blood, lung, and spleen of mice injected with lal−/− vs. lal+/+ MSCs plus B16 melanoma cells." (PMID 27531897, 2016). "Depletion of the CD4+ cell population had an intermediate effect on H1152-induced melanoma slowing down since it did not completely restore tumor growth to that of the control conditions." (PMID 26236689, 2015).
melanoma (continued). "Consistent with the present report, our previous study investigating the role of IL-17 in the context of CD4+ T-cell responses to TAAs documented a negative impact ofIL-17-producing T-cells in late-stage melanoma." (PMID 26500775, 2015). "Taken together, these data suggest that DRG-1 plays an important role in melanoma cell growth and transformation, indicating that DRG1 may represent a novel target for CD4+ T cell-mediated immunotherapy in melanoma." (PMID 25993655, 2015). "However, melanoma MHC class II expression correlates with metastatic disease and poor survival and the melanoma specific CD4+ T cells appeared as tumour tolerogenic." (PMID 25760947, 2015). "In this line, in low A-SMase expressing tumours we found low levels of DCs; of interest these cells also showed an immature and anergic phenotype, a typical feature of melanoma infiltrating DCs resulting in the inability to trigger the activation of tumour specific CD8+ and CD4+ T lymphocytes." (PMID 26101462, 2015). "CD8+ and CD4+ T-cells from these stimulated PBL were able to respond to DNP-modified lymphocytes, however, only CD8+ T-cells could respond to DNP-modified melanoma cells." (PMID 24949488, 2014). "One study presented results for risk of melanoma amongst individuals infected with HIV by recent CD4 count only, and reported elevated RRs for individuals with CD4 counts <200 and 201–499 cells/mL, but not for ≥500 cells/Ml." (PMID 24740329, 2014). "The entry of Tc17 and Th17 cells could elicit multiple antitumor immune responses, as CD4+ and CD8+ IL-17 producing T-cells have been shown to elicit tumor regression in melanoma mouse models." (PMID 24949488, 2014). "In contrast, without NDV infection, contact with autologous melanoma cells rendered the CD4 T cell clone non-reactive and un-responsive, even to subsequent stimulation by IL-2." (PMID 24833054, 2013). "To confirm whether CD8+ T cells are necessary for anti-melanoma effect of EW-7197, we deleted CD8+, CD4+ or NK cells in C57BL/6 mice inoculated with GFP-expressing B16 cells (2 × 105)." (PMID 24127404, 2013). "Overall, MELOE-1 specific CD4 T cells were not more frequently detected in melanoma patients’ PBMC than in healthy donors’ PBMC." (PMID 23284752, 2012). "Our observation that MA3/DP4-specific CD4 T cells recognize MA3-protein-loaded DC rather than MZ2-MEL43 melanoma cells implies that these CD4 T cells yield antitumor activity in vivo following cross-presentation by professional antigen presenting cells." (PMID 22400038, 2012). "This would suggest that overexpression of meloe messenger mRNA in tumor cells did not result in the expansion of specific CD4 T cells in vivo in melanoma patients." (PMID 23284752, 2012). "We further documented the reactivity of specific CD4 T cell clones to HLA-matched MELOE-1 expressing melanoma cell lines, in presence or absence of exogenous peptide." (PMID 23284752, 2012). "Since MA3/DP4 TCR T cells are unable to directly recognize antigen-positive melanoma cells, an ability that is generally expected only for antitumor CD8 T cells, we analyzed a more typical CD4 T-cell response that is based on (cross-) presentation of tumor antigens by DC." (PMID 22400038, 2012). "The current study now establishes that effective memory CD8 T cell responses against melanoma can be generated even in the complete absence of CD4 T cell help." (PMID 22046294, 2011). "However, our own studies have shown that memory CD8 T cell responses to melanoma/melanocyte differentiation antigens TRP-2 and gp100 can be generated despite early transient ablation of CD4 helper T cells." (PMID 22046294, 2011). "Anti-CD4 treatment did not impair primary tumor growth, although it induced concomitant immunity against re-challenge with melanoma tumors." (PMID 22046294, 2011).
melanoma (continued). "Implantation of the B16 melanoma in wild-type mice resulted in the enrichment of CD4 Foxp3 Treg in TIL and spleen; this tumor did not induce an enrichment of either CD4 or CD8 Foxp3 in these two transgenic mouse strains." (PMID 22112546, 2011). "We have previously shown that treatment of mice with anti-CD4 (mAb clone GK1.5) on days 4 and 10 of B16 melanoma tumor growth induces priming of a protective CD8 T cell response against melanoma differentiation antigens, as a result of CD4+CD25+ Treg depletion." (PMID 22046294, 2011). "Mice lacking total CD4 T cell help also mounted protection against re-challenge with B16 melanoma sixty days after primary tumor excision." (PMID 22046294, 2011). "In conclusion, phenotypic and functional analyzes strongly suggest that CD4+Foxp3GFP+ T cells that develop in melanoma tumors represent genuine Treg cells and not cells that transiently upregulate Foxp3 without acquiring suppressor function." (PMID 21049016, 2010). "Since depletion of CD25+ regulatory T cells (Treg) from PBMC has been demonstrated to enhance detection of antigen-specific CD4+ T cell responses, we additionally stimulated CD25-depleted PBMC from melanoma patients and healthy individuals with library peptide #19." (PMID 21152437, 2010). "CD4+ T cell epitopes thus identified were validated in the human system by stimulation of peripheral blood mononuclear cells (PBMC) from healthy donors and melanoma patients." (PMID 21152437, 2010). "In this section, we will discuss these self Ags and their antigenic determinants that may elicit both CD4+ and CD8+ T cell responses against HLA class I and II expressing melanoma cells." (PMID 20016802, 2009). "Half of the CD4+ clones derived exhibited cytotoxicity directly against recipient melanoma cells without killing a WMMH-derived EBV cell line, implying the clones did not recognise a minor histocompatibility antigen." (PMID 16819544, 2006). "More than half of the remaining noncytotoxic CD4+ clones released interferon-γ on exposure to the melanoma line." (PMID 16819544, 2006). "Both CD4+ and CD8+ melanoma-reactive T-cell subsets were isolated from skin biopsies of DTH sites." (PMID 14970852, 2004). "Although the pre-specified primary endpoint was not met, our findings identify activated CD4+/CD8+ T cell states and TCR persistence as key outcome-associated features, supporting immune-informed optimization of peri-operative therapy in mucosal melanoma." (PMID 42140948, 2026). "In a melanoma mouse model, we demonstrated that Ackr2 inhibition increases the release of proinflammatory chemokines CCL5 and CXCL10 and enhances the infiltration of NK cells, activated CD8+ and CD4+ effector T cells while reducing regulatory T cells (Tregs) in the TME." (PMID 40248897, 2025). "In melanoma, T cell phenotypic characterization of TILs and peripheral blood lymphocytes in patients treated with T-VEC demonstrated increased intratumoral CD8 + T cells, neutrophils, monocytes, and chemokines, as well as increased peripheral CD4 + T cells, CD8 + T cells, and myeloid populations." (PMID 41271741, 2025). "This revealed a significant positive correlation between melanoma ICAM-1high expression and increased infiltration of antitumorigenic M1 macrophages and CD8+ T cells and a negative correlation with infiltration of plasma cells and resting CD4+ T-regulatory cells." (PMID 39867570, 2025). "Using mouse melanoma and breast tumor models, we found that PU.1 inhibition by DB suppressed tumor growth, likely through promoting CXCL9 expression in TAMs, which enhances the tumor infiltration of lymphocytes, including CD4+ Th1, CD8+ cytotoxic T lymphocytes (CTLs), and NK cells." (PMID 40867314, 2025). "Further more, depletion of natural killer (NK) cells or CD4 + T cells in the SUP3-treated mice did not inhibit tumor growth in the B16F10 melanoma model, indicating that NK cells or CD4+ T cells were not the major cell types responsible for the SUP3-mediated antitumor response." (PMID 41291775, 2025).
melanoma (continued). "Although low‐dose cyclophosphamide has demonstrated effectiveness in enhancing antigen‐specific CD4+ T‐cell responses to the NY‐ESO‐1/ISCOMATRIX vaccine among individuals with advanced melanoma compared to vaccination alone, it has not yielded notable reductions in Tregs." (PMID 39275923, 2024). "Melanoma cell-intrinsic activation of GLI1 promotes changes in the infiltration of immune cells, leading to accumulation of immunosuppressive PMN-MDSCs and regulatory T cells, and to decreased infiltration of dendric cells (DCs), CD8 + and CD4 + T cells in the TME." (PMID 39090759, 2024). "Additionally, Gal-1 blockade has been reported to induce the positive regulation of CD4+ and CD8+ T-lymphocyte tumor infiltrates in pancreatic adenocarcinoma, head and neck carcinoma, melanoma, neuroblastoma, lung adenocarcinoma, ovarian carcinoma, and breast carcinoma." (PMID 39062081, 2024). "To address whether lack of CD4 T cells also contributes to melanoma growth restriction in H2-Aacit/cit mice, we generated H2-Aaflox/flox;Foxn1-cre mice, in which H2-Aa was deleted specifically in thymic epithelial cells, thus blocking CD4 T cell development." (PMID 39470607, 2024). "Furthermore, in another study analyzing flow cytometry data with supervised clustering from PBMCs in 90 advanced melanoma patients treated with anti-PD-1 and anti-CTLA-4 combinations, an increase in circulating CD4+ Tem cells correlated positively with longer PFS." (PMID 39273452, 2024). "Importantly, also CAFs directly isolated from a primary melanoma without further treatment (pMel CAFs) were potent in activating CD4 and CD8 T cells." (PMID 39516494, 2024). "Additionally, the presence of inflammatory (CXCL-11) and lymphoid (CXCL-13) chemokines has been associated with the recruitment of tumor infiltrating lymphocytes, namely CD4+ T cells, CD8+ T cells and mature dendritic cells, to promote melanoma cell destruction." (PMID 38812776, 2024). "In the melanoma cohort, PD-1 blockade responders (R) had significantly higher enrichment scores for the CD4+_MKI67 signature (p = 0.025) and the CD4+_CXCL13 signature (p = 0.05) than nonresponders (NR) did, indicating the predictive value of this cell population." (PMID 38383773, 2024). "However, the CD4+ T-cell and Treg populations in BRafV600E/Ptennull mouse melanomas were not affected by either Z36-MP5 alone or in combination with anti-PD-1 treatment in BRafV600E/Ptennull melanoma." (PMID 38461299, 2024). "Using a preclinical mouse model of B16-F10 melanoma overexpressing IDO1 (B16IDO), authors demonstrated that IDO-expressing tumors have marked increases in Treg frequency and upregulated expression of FoxP3 in tumor infiltrating CD4+ T cells compared to B16WT-tumor bearing mice." (PMID 37876966, 2023). "In this context, it is encouraging that CD4+ T cell-mediated anti-CSPG4 responses have been detected in both healthy individuals and melanoma patients, and that both CD8+ T-cell clones described herein were retrieved from the peripheral blood of a melanoma patient." (PMID 37849763, 2023). "Interestingly, in our study, additional proof that further reinforces the role of CD26high as a biomarker in metastatic melanoma patients is the finding that lower baseline levels of CD4+CD26high T cells were correlated significantly with reduced OS and PFS in melanoma patients." (PMID 37170241, 2023). "Similarly, the present study observed higher immune scores and higher abundance of M1 macrophages, CD4 + T cells, CD8 + T cells and NK cells in the high-MLDIS group, further suggesting the influence of these tumor-infiltrating immune cells on melanoma development." (PMID 37752452, 2023). "Also, significant clonotypic amplification of CD4+ Treg TILs was observed in HLA class II positive melanoma, while no significant amplification was observed in other types of TILs." (PMID 36646683, 2023).
melanoma (continued). "To assess whether the presence of tumor cells influenced the proliferation of specific subsets (CD8+, CD4+, DP, and DN) of iNKT cells, we collected iNKT cells after 12 days of expansion, both in the presence and absence of melanoma cell lines." (PMID 37444608, 2023). "Tumor regression in melanoma-bearing Nlrp3-/- mice was accompanied by significantly increased frequencies of tumor-infiltrating CD45+ leukocytes, CD8+ lymphocytes, which exhibited elevated IFN-γ expression, and NK1.1+ cells, as well as increased frequencies of CD4+ T cells, compared to WT mice." (PMID 36032139, 2022). "Early clinical studies used [111In]In-oxine labelling of CD4+ T-cells to investigate the homing of CD4+ T-cells in Hodgkin’s lymphoma lesions with SPECT imaging, and accumulation of adoptively transferred tumor infiltrating lymphocytes, previously expanded ex vivo, in melanoma patients." (PMID 35099641, 2022). "After mice immunization, they observed strong cellular immunity, including potent IFN-γ+CD4+ T cells, IFN-γ+CD8+ T cells, cytotoxic T lymphocytes and cytokine excretion in spleen and lymph node cells leading to significantly tumor growth suppression and prolonged survival of mice in melanoma models." (PMID 36338731, 2022). "Indeed, examination of CRLF2 gene expression in CD4+ T cells from human melanoma scRNA-seq data did not reveal higher expression of CRLF2 by GATA3+ Tregs compared with other CD4+ T cells." (PMID 36107619, 2022). "GILT expression in melanoma cells is anticipated to promote anti-tumor immunity by facilitating the presentation of MHC class II-restricted peptides by tumor cells in the microenvironment, which are the same set of epitopes presented by APCs and involved in priming CD4 T cell responses." (PMID 35565329, 2022). "More recently, studies have shown the contribution of CD4+ CTL in cancer cell eradication in human using RNAseq in multiple solid cancers (non-small-cell lung cancer, colorectal cancer, hepatocellular carcinoma, bladder cancer, osteosarcoma, breast cancer, head and neck cancer and melanoma)." (PMID 35008422, 2022). "In addition, assessment of lymph nodes with or without melanoma metastases has shown a lower CD4/CD8 ratio and decreasing IFNγ levels with increasing number of nodal metastases." (PMID 35336796, 2022). "Finally, ex vivo treatment with nPKC-θi2 increased the expression of TNF-α and IFN-γ in CD8+ T cells from responder and resistant patients with advanced melanoma, consistent with our previous work showing that PKC-θ inhibition regulates the expression of these cytokines in human memory CD4+ T cells." (PMID 35326747, 2022). "Both single and double immune checkpoint inhibitor-treated melanoma patients with other serious immune-related adverse events (irAE) (n=9) also expressed ICOS on a significantly higher proportion of CD4+ and CD8+T cells compared with controls without irAE (n=12)." (PMID 34215689, 2021). "Secondary follicular TLS in human melanoma metastases regularly contained key cellular and molecular components in a typical spatial arrangement, but only some larger secondary follicular TLS (21.7%) contained germinal centers that included BCL6+CD20+ B cells with interspersed BCL6+CD4+ T cells." (PMID 34248957, 2021). "For a mixed population of GZMB+ and GZMK+ CD4+ in melanoma, higher RUNX3 and PRDM1 (BLIMP-1) expression was predominant over low-level TBX21/EOMES expression, and the PRDM1 overexpression is supported by similar findings from GZMB+ CD4+ T cells in murine adenoviral infection." (PMID 34910940, 2021). "Two years later, the same group and Catherine Wu’s group published back-to-back reports reporting clinical findings showing that personalised neoantigen vaccines for melanoma patients primarily induced tumour-specific responses in CD4+ rather than CD8+ T cells." (PMID 32457487, 2021).